NTN1 (netrin 1)
Diseases named in the same sentence as NTN1 in open-access papers (continued):
Sharing a sentence is not in itself a finding about the gene and the disease.
Cognitive impairment (13 papers, 2019 to 2025). Abnormal cognition is characterized by deficits in thinking, reasoning, or remembering. "After controlling for baseline data, multiple regression analysis revealed that Netrin-1 remained an independent risk factor for cognitive impairment after SCI (=0.274, p = 0.036)." (PMID 35493300, 2022). "Besides AD, the serum Netrin-1 is also found to decrease in clinical patients with spinal cord injury and can be an independent risk factor for cognitive impairment in these patients." (PMID 38638604, 2024). "In addition, the association among netrin-1, cognitive impairment and serum inflammatory cytokines such as interleukin-17 (IL-17) and tumor necrosis (TNF-α) remains unclear." (PMID 35250531, 2021). "However, the change of serum netrin-1, along with the association among netrin-1, cognitive impairment and serum cytokines (IL-17 and TNF-α) in AD/MCI patients remains unclear." (PMID 35250531, 2021). "Accordingly, this study aimed to investigate the effects of NTN-1 on cognitive impairment and to explore the anti-inflammatory properties related to the NLRP3 inflammasome and NF-κB signaling in Aβ1-42-induced rat models." (PMID 40357234, 2025). "Although data on Netrin-1's significance in neurological illnesses and SCI have begun to appear in recent years, its association with cognitive impairment remains uncertain." (PMID 35493300, 2022). "The study of Netrin-1 as a potential serum marker of cognitive impairment after SCI will be helpful for the treatment and rehabilitation of cognitive impairment after SCI." (PMID 35493300, 2022). "The goal of this study was to see if there was a link between serum Netrin-1 and cognitive impairment following a spinal cord injury." (PMID 35493300, 2022). "Our research is the first to show a link between Netrin-1 and cognitive impairment following a spinal cord injury." (PMID 35493300, 2022). "Here we show that amphetamine, by dysregulating Netrin-1/DCC signaling, triggers ectopic growth of mesolimbic dopamine axons to the prefrontal cortex, only in early-adolescent male mice, underlying a male-specific vulnerability to enduring cognitive deficits." (PMID 37419977, 2023). "Netrin-1 may be a neuroprotective factor for cognitive impairment, which may serve as a serum marker to predict cognitive impairment after SCI." (PMID 35493300, 2022). "The level of serum Netrin-1 may be a serum marker for predicting cognitive impairment after SCI, and a deeper understanding of its mechanism could modify the prevention and treatment strategy for cognitive impairment after SCI." (PMID 35493300, 2022). "Our study is the first to report the involvement of Netrin-1 in cognitive impairment after SCI." (PMID 35493300, 2022). "Based on the findings reported here, netrin-1 may serve as a marker for the early recognition of dementia and predict cognitive impairment." (PMID 35250531, 2021). "Netrin-1 concentrations were significantly down regulated in both serum and cerebrospinal fluid (CSF) of these AD rats, effects which were strongly correlated with cognitive deficits." (PMID 31191297, 2019). "In AD, the serum Netrin-1 protein levels are lowered in AD and MCI (mild cognitive impairment) patients and correlated with reduction in dementia scores." (PMID 38638604, 2024). "The goal of this study was to look at how serum Netrin-1 changed in the acute phase after SCI and how that related to cognitive impairment." (PMID 35493300, 2022). "The purpose of this study was to determine the changes of serum Netrin-1 after SCI and its relationship with cognitive impairment." (PMID 35493300, 2022). "Here, we present the first evidence that decreased serum netrin-1 levels in AD and MCI patients, are positively correlated with cognitive deficits." (PMID 35250531, 2021).
depression (13 papers, 2019 to 2026). "Genetic variations of Netrin-1/DCC have been shown to associate significantly with depression, schizophrenia, and substance use." (PMID 38638604, 2024). "Genetic variations of Netrin-1/DCC have been shown associate significantly with depression, schizophrenia, and substance use." (PMID 38638604, 2024). "Further confirmation of the Netrin-1/DCC system as a depression risk marker comes from a recent study that integrated multi-omics data." (PMID 37035502, 2023). "The Lbp-Tlr4-Netrin-1 axis was highly upregulated in depressed subchondral bone, and its inhibition alleviated both pain-like behaviors and excessive bone resorption while mitigating depression-related weight loss." (PMID 41711199, 2026). "Recently, a UK Biobank study (n = ~6400) found that the SNPs in the Netrin-1 signaling pathway conferring risk for major depression are associated with altered white matter microstructure in thalamic radiations, namely lower fractional anisotropy and higher mean diffusivity." (PMID 31659271, 2020). "Moreover, using pathway analyses in two independent samples (n = 6455, n = 18,759), FDR-corrected associations between depression and a Netrin-1 signaling pathway were identified, comprising SNPs from multiple genes involved in Netrin-1 signaling, including DCC." (PMID 31659271, 2020). "Within this context, it is worth mentioning that NTN1 has been identified as a candidate gene for psychiatric disorders, including depression." (PMID 38540364, 2024). "Specifically, elevated NTN‐1 levels were associated with increased severity in motor function (H‐Y stage and UPDRS scores) and potential depression (HAMD score)." (PMID 39215401, 2024). "Positive correlations were found between NTN‐1 levels and motor, depression, and cognitive symptoms." (PMID 39215401, 2024). "The potential target genes Ntn1, Unc5b, Ptpn11, and Src are included in this pathway and participate in the process of psychiatric disorders such as depression." (PMID 37091805, 2023). "Taken together, these findings suggest that alterations in the Netrin-1/DCC guidance cue system in the PFC predispose rodents to stress-induced susceptibility and depression-like behaviors, while also being associated with MDD in humans." (PMID 37035502, 2023). "As Cdh8, Cdh13, and Dcc/Netrin-1 have been linked to ASD, depression, and schizophrenia, investigating their role in wiring the healthy brain can provide important clues about how mPFC circuitry is perturbed in disease." (PMID 33949949, 2021). "Our study has observed a downregulation of netrin-1, a crucial factor for axon guidance, after MIN administration, supporting netrin-1 as a promising candidate for depression treatment." (PMID 31695615, 2019). "HMGB1 and netrin-1 are key factors involving in several neuroinflammatory conditions including depression." (PMID 31695615, 2019). "Depression-associated pairs spanned Notch (JAG1-NOTCH2, DLL1-NOTCH3, DLL4-NOTCH3), ephrin (EFNA5-EPHA5, EFNA5-EPHA7, EFNA5-EPHA4), and extracellular matrix pathways (SLIT1-ROBO1, NTN1-DCC)." (PMID 40964296, 2025). "In addition, Netrin-1 was previously proved to be a major contributor to both neuropathic pain and psychiatric conditions like depression." (PMID 35966013, 2022). "This may help explain the association of different genetic variants of Netrin-1 and DCC with depression, schizophrenia or substance use." (PMID 33195252, 2020). "In addition, results from human postmortem examinations, animal work and GWAS studies suggest that the relevance of the Netrin-1/DCC pathway in the etiology of major depressive disorder due to its abnormal spatiotemporal organization of circuits involved in cognition and emotion." (PMID 38638604, 2024). "Subsequent partial correlation analysis revealed a positive correlation between higher NTN‐1 levels and increased severity of motor symptoms (H‐Y stages and UPDRS scores), depression (HAMD scores), and cognitive function (MMSE and MoCA scores) in PD patients." (PMID 39215401, 2024).
acute kidney injury (12 papers, 2011 to 2026). Sudden and sustained deterioration of the kidney function characterized by decreased glomerular filtration rate, increased serum creatinine or oliguria. "The agents or stimuli that are known to induce acute kidney injury and the associated increase in netrin-1 in vivo also induced netrin-1 in vitro in TKPTS cells, which was again mediated through ERK MAPK pathways." (PMID 22046354, 2011). "An ERK mediated increase in netrin-1 production was also seen in vitro with drugs that are known to cause acute kidney injury." (PMID 22046354, 2011). "Our earlier studies identified netrin-1 as an early diagnostic biomarker of acute kidney injury." (PMID 22046354, 2011). "Therefore, netrin-1 was identified as an early diagnostic biomarker of acute kidney injury (AKI) in mice as well as in humans." (PMID 22046354, 2011). "Ramesh G, Krawczeski CD, Woo JG, Wang Y, Devarajan P. Urinary netrin-1 is an early predictive biomarker of acute kidney injury after cardiac surgery." (PMID 32267322, 2020). "Urinary netrin-1 was elevated in patients with acute kidney injury after cardiac surgery and was suggested to be an early predictive biomarker of acute kidney injury before the rise of serum creatinine." (PMID 30532735, 2018). "Our in vivo study shows that drugs, such as endotoxin and cisplatin that are known to induce acute kidney injury increased netrin-1 production from kidney tubules and are excreted in the urine." (PMID 22046354, 2011). "Additionally, examination of human urine samples with acute kidney injury revealed elevated netrin-1 levels throughout all categories of AKI." (PMID 36648873, 2022). "Netrin-1 is an early biomarker of acute kidney injury Netrin-1 and kidney injury." (PMID 32267322, 2020). "Furthermore they showed that urinary netrin-1 excretion is increased in patients following acute renal failure compared to urine from healthy controls suggesting netrin-1 as an early biomarker for acute renal failure." (PMID 21625583, 2011). "Since oxidative stress and MAPK activation are prominent events after ischemia reperfusion and other forms of acute kidney injury, we used pervanadate to investigate the influence of cellular stress on the netrin-1 production in mouse proximal tubular epithelial cells (TKPTS)." (PMID 22046354, 2011). "The 6-h urine netrin-1 measurement strongly correlated with duration and severity of AKI (acute kidney injury), as well as length of hospital stay (all p < 0.05)." (PMID 33669495, 2021). "Despite the abundant netrin-1 expression in the tubular epithelial cells following kidney IR, the additional systemic administration of netrin-1 and the renal overexpression of netrin-1 attenuate systemic inflammation, neutrophil and monocyte influx, and renal failure." (PMID 35008701, 2021). "Netrin-1 is also known to regulate inflammatory cell migration and their functions in many diseases and suppress acute kidney injury (AKI)." (PMID 27176224, 2016). "Here, we hypothesized an anti-inflammatory role of endogenous netrin-1 in acute kidney injury (AKI)." (PMID 21625583, 2011).
Cerebral ischemia (12 papers, 2013 to 2023). Restriction of arterial blood supply to the brain associated with insufficient oxygenation to support the metabolic requirements of the tissue. "Further, axon repair and nerve regeneration were promoted after cerebral ischemia through Netrin-1/Rac1/Cdc42 signalling pathways." (PMID 36975497, 2023). "Taken together, our results indicate that Netrin-1 can promote neural functional recovery after the cerebral ischemia." (PMID 29487502, 2018). "This study extends our understanding of Netrin-1’s role in neural regeneration and provides further evidence for its potential value in the cerebral ischemia therapy." (PMID 29487502, 2018). "In the research of cerebral ischemia, in vivo, Netrin-1 was up-regulated after middle cerebral artery occlusion." (PMID 29321724, 2017). "Secondly, while during development neurons move through Netrin-1 gradients gradually, under pathological conditions, e.g., brain ischemia or spinal cord injury Netrin-1 levels change much more rapidly." (PMID 28105005, 2016). "The study aimed to estimate the efficacy of dexmedetomidine and Netrin-1 combination therapy against ERS-induced apoptosis after cerebral ischemia injury in vivo and in vitro, and whether the mechanism is related to the ERK5/MEF2A pathway." (PMID 33584197, 2021). "However, little literature is available to shed light on Netrin-1’s mechanism in neural remodeling after the cerebral ischemia." (PMID 29487502, 2018). "Altogether, these findings suggest that Netrin-1 can improve the outcome of cerebral ischemia." (PMID 29321724, 2017). "Endogenous Netrin-1 (NT-1) protein was significantly increased after cerebral ischemia, which may participate in the repair after transient cerebral ischemic injury." (PMID 27746720, 2016). "Furthermore, in our previous study, after the occurrence of cerebral ischemia, netrin-1 may play an important role in axon regeneration, forming new neural circuits by acting with DCC54." (PMID 27456198, 2016). "The combination of dexmedetomidine and netrin-1 has been shown to decrease ER stress by activating ERK5, consequently preventing cerebral ischemia-reperfusion injury." (PMID 35609325, 2022). "Combination of dexmedetomidine and Netrin-1 resulted in lower infarct volumes and fewer neurological impairments, higher OPS recovery rate, and less damaged and apoptotic cells after cerebral ischemia injury." (PMID 33584197, 2021). "Our previous study found that treadmill exercise significantly increased the expression of Netrin-1 and its receptor DCC after the acute stage of cerebral ischemia injury." (PMID 29487502, 2018). "The results demonstrate that Netrin-1 promotes both pre-synaptic and post-synaptic formation partly via the activation of the JNK1/c-Jun signaling pathway after the cerebral ischemia." (PMID 29487502, 2018). "Taken together, these findings suggest that Netrin-1 can facilitate the synaptic formation and axonal regeneration via the JNK1 signaling pathway after cerebral ischemia, thus promoting the recovery of neural functions." (PMID 29487502, 2018). "Previous studies have found that Netrin-1 has a protective effect on the permeability of the blood-brain barrier and can stabilize neurons without sustained damage after cerebral ischemia, which is related to the alleviation of apoptosis." (PMID 33584197, 2021). "Moreover, injection of netrin-1 attenuated GFAP expression (netrin-1 0.27 ± 0.06 vs. BSA 0.62 ± 0.04, p < 0.001) and the release of interleukins and reduced infarct volume after brain ischemia (netrin-1 0.27 ± 0.06 vs. BSA 0.62 ± 0.04 mm3, p < 0.05)." (PMID 30227858, 2018). "Therefore, the upregulation of Netrin-1 and DCC receptors may be an endogenous protective effect after cerebral ischemia or hemorrhage." (PMID 35806983, 2022).
diabetic nephropathy (12 papers, 2011 to 2025). "Mice with partial Netrin-1 deficiency demonstrate severer kidney injury in with diabetic nephropathy which can be restored by treatment with recombinant Netrin-1." (PMID 38638604, 2024). "Diabetic nephropathy is associated with increased proteinuria which may induce netrin-1 production." (PMID 22046354, 2011). "These inflammatory suppressant actions of Netrin-1 were proposed to modulate not only diabetic nephropathy but also the progression of various microvascular diabetic complications." (PMID 34179515, 2021). "Recent studies report that netrin-1 protects the kidney against ischemia-reperfusion injury and attenuates diabetic kidney disease." (PMID 27176224, 2016). "This indicates the protective role of the anti-inflammatory molecule netrin-1 in diabetic kidney disease; in particular, specific overexpression of netrin-1 in proximal tubular epithelial cells suppressed inflammation and albuminuria." (PMID 27176224, 2016). "Like acute kidney injury, chronic kidney diseases such as diabetic nephropathy also show enhanced production of netrin-1 and increased levels in urine (unpublished observation)." (PMID 22046354, 2011). "In diabetic nephropathy, Ntn1 has been proposed as an early biomarker of tubular damage by inflammation with low serum concentrations of this molecule, which may lead to chronic kidney disease accompanied by loss of renal function." (PMID 36661496, 2022). "In diabetic nephropathy mice model, the mean level of serum netrin-1 was about 100 pg/mL." (PMID 30532735, 2018). "Additionally, in I/R injury of the kidney, downregulation of netrin-1 enhances inflammatory processes whereas overexpression of netrin-1 induces vascular regeneration and suppresses inflammation and apoptosis in diabetic nephropathy." (PMID 29059224, 2017). "Urinary netrin- 1 excretion was found to be markedly elevated by tubular epithelial cells in various acute and chronic kidney diseases including diabetic nephropathy and acute renal ischemia; however, its pathophysiological role in DKA-induced tubulopathy is still unknown." (PMID 40332546, 2025). "However, it is yet unknown how Netrin-1 affects renal proximal tubule cells in diabetic nephropathy (DN) under pathological circumstances." (PMID 38033740, 2023). "In this review, we focus on the early glomerular and tubular structural alterations, with a detailed description of the glomerular injury markers SMAD1 and Podocalyxin, and the tubular injury markers NGAL, Netrin-1, and L-FABP in the context of diabetic nephropathy." (PMID 36425298, 2022). "In type I diabetic animals, Netrin-1 expression was increased in proximal renal tubular epithelial cells and Netrin-1 was significantly elevated in the early phase without microalbuminuria and the late phase of all diabetic nephropathies compared to controls." (PMID 36425298, 2022).